CCND1 (cyclin D1)
Diseases named in the same sentence as CCND1 in open-access papers (continued):
Sharing a sentence is not in itself a finding about the gene and the disease.
breast cancer (continued). "In addition, ectopic expression of HOXA1 in MCF7 breast cancer cells upregulated cyclin D1, a cyclin that is required for steroid-induced proliferation of mammary epithelium during pregnancy and promotes the development of mammary adenocarcinomas when overexpressed." (PMID 24586203, 2014). "In addition, targeting SOX2 in breast cancer cell lines have shown that siRNA-mediated knock-down of SOX2 resulted in cell cycle arrest by down-regulation of Cyclin D1 and this arrest in cell cycle was accompanied by an inhibition of tumor cell proliferation in xenograft models." (PMID 24404135, 2014). "Furthermore, we have demonstrated that TBLR1 may promote proliferation and tumorigenicity in breast cancer through cyclin D1-transactivation and activation of the β-catenin signaling pathway." (PMID 25341494, 2014). "Our results suggest that amplification of RSF1 – but not that of the gene encoding for cyclin D1 – may be a candidate predictive biomarker for adjuvant tamoxifen benefit in this high-risk early breast cancer population." (PMID 24367492, 2013). "Because the breast cancer cell lines overexpressed cyclin D1, and cyclin A protein levels were elevated following irradiation, we tested whether knockdowns of their respective kinase partners CDK4 and CDK2 might alter the relative radioresistance of various breast cancer cell lines." (PMID 23886499, 2013). "Therefore, eugenol-related down-regulation of NF-κB and β-catenin and their common downstream target cyclin D1 could have a great inhibitory effect on breast cancer growth." (PMID 24330704, 2013). "However, the role of cyclin D1/CDK4/CDK6 in breast cancers is highly controversial." (PMID 23886499, 2013). "In addition, they first proposed that ectopic expression of cyclin D1 leads to increased radioresistance in breast cancer cells by enhancing DNA repair in the radioresistant cells, as downregulation of cyclin D1 in this system abrogated enhanced DNA repair, resulting in radiosensitivity." (PMID 23886499, 2013). "Moreover, we found TGFβ to induce complex formation and nuclear co-localization of cyclin D1 and p21, indicating that these two proteins may cooperate to mediate TGFβ functions in aggressive human breast cancer cells." (PMID 23786849, 2013). "Moreover, more than 20 common genetic variants have been shown to contribute to breast cancer risk; among these, the fibroblast growth factor receptor 2 (FGFR2) polymorphism rs2981582 as well as loci close to the cell cycle regulator Cyclin D1 (CCND1) at 11q13 are the most prominent risk loci." (PMID 23781229, 2013). "Thus cyclin D1 is one of the most overexpressed oncogenes in human breast cancer." (PMID 23320178, 2012). "A clear cut association between CCND1 amplification and patients’ outcome in female breast cancer is lacking, but CCND1 amplification may be associated with a poor prognosis, particularly in ER positive tumors." (PMID 22527098, 2012). "Cyclin D1 overexpression is responsible for the cell cycle deregulation playing a significant role for a greater aggressiveness, tumour extension, regional lymph node metastases and advanced clinical stage in many cancer types, such as oral cancer, breast cancer and lung cancer." (PMID 22770229, 2012). "In addition CCND1 amplification seems to be an independent prognosticator in male breast cancer." (PMID 22527098, 2012). "Moreover, differences in tamoxifen response in relation to cyclin D1 in postmenopausal versus premenopausal breast cancer might exist." (PMID 22475046, 2012). "Moreover cyclin D1 amplification and gain copies with consequent protein over-expression have been frequently described in multiple myeloma, T cutaneous lymphomas and in solid cancer, such as oral squamous cell carcinoma, lung cancer, melanoma, breast cancer." (PMID 22770229, 2012).
breast cancer (continued). "This may partly explain the conundrum that high cyclin D1 is associated with non-proliferating breast cells and also aggressive highly proliferative breast cancer." (PMID 22860097, 2012). "Moreover, we have confirmed a relationship between cyclin D1, Id1 and EMT in primary breast cancer, supporting our in vitro findings that low cyclin D1 expression can be linked to aggressive features in subgroups of breast cancer." (PMID 21955753, 2011). "The aim of this study was to examine whether inhibition of type-2A phosphatases would promote degradation of cyclin D1 levels in human breast cancer cells, exposing a mechanism by which small molecule inhibitors may aid in suppression of tumor cell proliferation." (PMID 22069692, 2011). "Interestingly, over expression of Cyclin D1 sensitizes breast cancer cells to 4-HPR." (PMID 21951911, 2011). "Additionally, the ability of the derivatives to significantly decrease the survival of glioma and breast cancer cell lines indicates that they may be of general interest for treating cancers that respond to 4-HPR or depend on Cyclin D1 for growth." (PMID 21951911, 2011). "Indeed, in breast carcinoma specimens, we observed that overexpression of MUC1-C was associated with a nuclear distribution of β-catenin in tumor tissues and increased expression of Cyclin D1 and c-Myc." (PMID 21533058, 2011). "The role of cyclin D1 in breast cancer remains unclear showing varying correlation to prognosis." (PMID 19615042, 2009). "Thus suppression of cyclin D1 expression could play a major role in breast cancer prevention in the future." (PMID 19640308, 2009). "Despite several studies, the exact role of cyclin D1 in breast cancer remains unclear." (PMID 19615042, 2009). "However, recent analyses revealed that the ability of estrogen to induce cyclin D1 in breast cancer cells can be executed though an enhancer region downstream of the cyclin D1 coding region, and involves recruitment of ERβ to that locus (M. Brown, personal communication)." (PMID 16863592, 2006). "Anti-cyclin D1 therapy may be thus be important for treating human breast cancer." (PMID 16504004, 2006). "Thus, in breast cancer cells it was proposed that cyclin D1 could use both CDK dependent mechanisms and CDK independent mechanisms to promote proliferation." (PMID 16863592, 2006). "For selected tumor types, cyclin D1 has been postulated as a potential target for therapeutic intervention (e.g. pancreatic and breast cancer), and how the disparate functions of cyclin D1b may influence outcome should likely be incorporated as a major consideration." (PMID 16863592, 2006). "Consistent with this hypothesis are reports of elevated cyclin D1 mRNA levels and immunohistochemically detectable accumulation of the protein in over one third of breast cancer cases at a frequency significantly higher than that deduced from DNA amplification studies." (PMID 15385053, 2004). "Cellular experiments confirmed that DSN1 promotes breast cancer proliferation by affecting cell cycle pathways, involving key molecules such as CCNB1, CCND1, CKD1, CDK4, and CDK6." (PMID 41640445, 2026). "The interplay between the Cyclin D1 and PI3K/AKT/mTOR signaling pathways in breast cancer is of paramount importance in tumor progression and drug resistance development." (PMID 41348684, 2025). "In canonical cell cycle machinery, cyclin D1/CDK4 initiates RB phosphorylation and activates CDK2, as observed in ER+ breast cancer models." (PMID 39924553, 2025). "The mechanistic exploration revealed that PAX7 influences breast cancer through the Wnt/β‐catenin signalling pathway, resulting in reduced expression of β‐catenin, c‐MYC, and Cyclin D1 when PAX7 is suppressed." (PMID 40370330, 2025).
breast cancer (continued). "Cyclin D1 interacts with a newly emerged long non-coding RNA DILA1, which is greatly upregulated in tamoxifen-resistant breast cancer cells." (PMID 41348684, 2025). "A greater frequency of CCND1 amplifications is observed in ER-positive subsets of breast cancer patients, and a shorter DFS for the ER-positive subset of CCND1-amplified patients has been reported." (PMID 39586971, 2025). "Breast cancer treatment involves targeting key genes involved in cell proliferation, differentiation, and apoptosis, such as PIK3CA, CCND1, HER2, STAT3, WNT1, and KRAS." (PMID 40284420, 2025). "The purpose of this study was to determine the prognostic value of CCND1 amplification and its correlation with clinically established biomarkers in patients with HR-positive HER2-negative primary breast cancer." (PMID 39586971, 2025). "Transfection of dCas9-DNMT3A constructs alongside guide constructs resulted in significant decreases in the gene expression of CCND1 in both MCF7 and MB-MDA-231 breast cancer cell lines." (PMID 39940977, 2025). "EMT transcription factors such as SNAIL and ZEB2 can inhibit cell cycle transition by inhibiting the transcription of CCND2 and CCND1, respectively, ZEB1 protein degradation induced by CDK4/6 inhibition blocks breast cancer metastasis." (PMID 39949984, 2025). "The administration of nano-curcumin has been shown to reduce the expression of the Cyclin D1 and DILA1 genes, as well as downregulate the PI3K/AKT/mTOR signaling pathway, and furthermore, induce apoptosis in tamoxifen-resistant breast cancer cells." (PMID 41348684, 2025). "Others have shown that this phenolic compound can mimic the effects of anti-oestrogens by altering key growth regulatory signals involving ER/cyclin D1 and IGF1R/p-AKT, thereby reducing the proliferation of breast cancer cells." (PMID 40493253, 2025). "We found that SSD can decrease CCND1 level, which highlighted the potential of SSD in the treatment of ER + breast cancer." (PMID 40708058, 2025). "The upregulation of cyclin D1 and BCL2 via ERα signaling correlates with an enhanced proliferative response in breast cancer cells." (PMID 40283136, 2025). "Cyclin D1 and BCL2 gene overexpression is identified in the earliest stages of breast cancer development, such as ductal carcinoma in situ, and is maintained in all phases of metastasis." (PMID 40283136, 2025). "CCND1 amplification was therefore defined as a CCND1 probe to CEP11 ratio of 2.0 or greater—the same ratio recommended by the U.S. Food and Drug Administration for HER2 amplification diagnosis for breast cancer." (PMID 39586971, 2025). "Given that tumor growth often relies on uncontrolled cell cycle progression, the cyclin D1/CDK4/6 axis has emerged as a key target for cancer therapy, including breast cancer." (PMID 40244377, 2025). "This research investigates the effects of nano-curcumin on the expression of Cyclin D1 and DILA1 genes, as well as on the PI3K/AKT/mTOR pathway, in tamoxifen-sensitive and resistant MCF-7 breast cancer cell lines." (PMID 41348684, 2025). "In breast cancer models, resveratrol suppresses tumorigenesis via modulation of EGFR signaling pathways, induction of G0/G1 cell cycle arrest, and downregulation of cyclin D1 expression." (PMID 41291133, 2025). "The rationale for choosing Cyclin D1 and BCL2 genes for gene expression research is that overexpression of cyclin D1 and BCL2 has been reported in over 50% of human breast cancers of all histological types." (PMID 40283136, 2025). "In MDA-MB-231 breast cancer cells, oncogenes such as PIK3CA, CCND1, HER2, and WNT1 were significantly downregulated, particularly in the FEO-CSNP treatment group, indicating the suppression of proliferative and metastatic signaling pathways." (PMID 40284420, 2025).
breast cancer (continued). "In fact, several studies have shown that E2 controls the Cyclin D1, c-Myc, CDK2, CDK4, and CDK inhibitors in MCF-7 breast cancer cells, thus promoting the progression from the G1 to S phase of the cell cycle." (PMID 40801565, 2025). "This increases Stat5a-mediated transcription and elevates the protein expression of breast cancer proliferative genes, such as CISH, CEBPb (CCAAT/enhancer binding protein β), and cyclin D1, which promote the proliferation of breast cancer." (PMID 40092489, 2025). "In ER + breast cancer, FGFs and FGFR1 amplification promote proliferation by activating MAPK signaling and increase cyclin D1 levels." (PMID 38553760, 2024). "We observed more than a 2.2-fold increase in CCND1 and 2.8-fold increase in RRM2 expression in PLB-resistant as compared to parental ER+ MCF7 breast cancer cells." (PMID 38473336, 2024). "This is consistent with previous studies on breast cancer, showing that MUC1 influences cell proliferation by inducing EGF receptor (EGFR) nuclear translocation and increasing its binding affinity with the cyclin D1 gene promoter." (PMID 38254882, 2024). "The dependence of breast cancer on CDK4/6 and its binding partner cyclin D1 for progression through the G1/S phase of the cell cycle has made breast cancer a prime target for the implementation of CDK4/6 inhibitor-based therapy." (PMID 38730702, 2024). "Collectively, HER2 knockdown significantly induced G1 phase arrest, decreased the expression of Cyclin D1 and CDK4, and enhanced the inhibitory effect of CDK4/6 inhibitor combined with endocrine therapy on HR+/HER2-low breast cancer cells." (PMID 39730704, 2024). "The inhibition of ribonucleotide reductase by DDX alone or in combination with palbociclib decreases RRM2 and cyclin D1 and pRb levels in MCF7 ER+ breast cancer cells." (PMID 38473336, 2024). "Notable exceptions include cytobands 8q24.21 (in TNBC) and 11q13.2–5 (in luminal), which harbor prevalent breast cancer oncogenes MYC and CCND1, respectively, and are frequently amplified." (PMID 38260372, 2024). "One analysis of primary breast cancer samples revealed that ERBB2, FGFR1, MYC, CCND1, and PIK3CA were commonly amplified, and other well-known oncogenes such as CCND2, EGFR, FGFR2, and NOTCH3 were amplified at lower frequencies." (PMID 38611020, 2024). "We also observed an upregulation of cyclin D1 and RRM2 protein levels in ER− palbociclib-resistant breast cancer cells, which suggests a possible mechanism for the development of palbociclib resistance." (PMID 38473336, 2024). "TIMER2.0 was used to estimate the correlations between ESR1, with a purity adjustment, and the expression of CTSD, EGFR, CCND1, and BCL2 in breast cancer subtypes." (PMID 39202273, 2024). "Clinically relevant amplification drivers such as ERBB2 in breast cancers (FF: 7.7%, FFPE:4.7%), GNAS (20q13) in colorectal cancers (FF: 6.4%, FFPE: 4.5%), and CCND1 (FF: 6.9%, FFPE: 8.5%) were comparably retrieved." (PMID 39231944, 2024). "Immunoblot further verified that neratinib effectively downregulated Cyclin D1, CDK4 and EGFR by inhibiting the HER2 pathway, thus enhancing the efficacy of CDK4/6 inhibitor combined with endocrine therapy in HR+/HER2-low breast cancer (P < 0.01)." (PMID 39730704, 2024). "This impact was correlated with a notable decrease in the mRNA levels of cyclin D1 and cyclin-dependent kinase (CDK4) in both breast cancer cell lines." (PMID 38563878, 2024). "Specifically, in breast cancer, ZKSCAN3 expression exhibits a positive correlation with CCND1 and BCL2 expression, while it negatively correlates with the expression of Bcl2 Associated X Protein (Bax)." (PMID 39519085, 2024). "On another note, breast cancer patients with wtCCND1 and unmethylated (unm) PCDH17 achieved higher pCR rate than those with CCND1 amp andmethylated (m) PCDH17 (13.8% (n=1) vs 2.7% (n=1) and 67.3% (n=1) vs 31.6% (n=1), respectively)." (PMID 38576013, 2024).
breast cancer (continued). "We also found upregulation of cyclin D1, AKT and RRM2 with palbociclib resistance in MDA-MB-468 breast cancer cells compared to parental cells." (PMID 38473336, 2024). "In line with the MTT data and cell cycle analysis, the well-known genes that regulate cell proliferation and cell cycle progression, including Cyclin D1 and PCNA, were significantly downregulated when PNKY was knocked down in breast cancer cells." (PMID 37104007, 2023). "This miRNA had anteriorly been described to alter the cell cycle by affecting CCND1 (cyclin D1), CDKN2A, or the induction of the exit from the quiescent state of the mammary cancer stem cells." (PMID 37046799, 2023). "Our previous study demonstrated that IGFBP-3 induced G1 cell cycle arrest by inhibiting cyclin D1, cyclin D3, cyclin E, cyclin A, CDK2, CDK4, total and phospho-pRb, and increasing p21 and p16 in MCF-7 breast cancer cells." (PMID 37253773, 2023). "In breast cancer cells, TCF12 stimulates the activation of c-MYC/Cyclin D1 pathway to accelerate cancer growth via facilitate CXCL12 of CAFs." (PMID 36721232, 2023). "The expression of cyclin D1 decreased (2.8-fold) only in resistant cells after 4 nM docetaxel treatment, while this marker was unchanged in parental MCF7 breast cancer cells." (PMID 37065867, 2023). "In serum-stimulated liver cancer (HepG2, HuH7, and SK-Hep1) and breast cancer (MCF7) cells, knockdown of cyclin D1 led to decreased cell cycle progression (as measured by DNA synthesis) and diminished lactate production." (PMID 38152849, 2023). "LAQ824 reduced the expression of ERα, PRβ, c-Myc, cyclin D1 and HDAC6 in breast cancer cells, leading to suppression of cellular proliferation." (PMID 36969235, 2023). "The mRNA from cyclin D1 (CCND1) and thymidylate synthase (TYMS) served as reliable predictive biomarkers in breast cancer." (PMID 37091783, 2023). "The expression levels of ERBB2, CCND1, and BCL2 were significantly higher in the breast cancer component than in the FAs." (PMID 37328469, 2023). "Thus, given that melatonin acts as a proteasome inhibitor, its effects on the inhibition of cyclin D1 and E, CDK2, CDK4 and c-Myc expression in brain cancer stem cells or on the reduction of cyclin D1 and E expression in breast cancer cells could be closely linked." (PMID 36768253, 2023). "Treatment of human breast cancer cells with the PR agonist medroxyprogesterone acetate led to an enhancement in the interaction between AIB1 and PR and a recruitment to cyclin D1 and Myc promoters." (PMID 37711895, 2023). "For instance, the medium of CAF induces cyclin D1, c-MYC, MMP-2 and MMP-9 expression in breast cancer cells, accelerating proliferation, migration and invasion." (PMID 36721232, 2023). "In breast cancer (BC), CDK-cyclin pathways are constitutively activated by events, such as cyclin D1 overexpression." (PMID 37958338, 2023). "For example, in breast cancer cells, CCN3 increased cell proliferation by upregulating the expression of cyclin D1." (PMID 37373471, 2023). "About 20% of HER2+ breast cancers had abnormal CTTN copy numbers and/or expression, and the frequencies for CCND1 were similar, while alterations in the other genes were found at relatively low frequencies." (PMID 36831511, 2023). "FOXM1, a forkhead family of transcription factor, is involved in the regulation of cell proliferation and mitosis by regulating transcription of p27kip1, cyclin D1, cdc25, KIF20A, and CENP-A in breast cancer." (PMID 37025658, 2023). "We also found that PCK2 promoted cell cycle progression, particularly the G1/S transition, and induced upregulation of E2F1, cyclin D1, cyclin D2, and CDK4 in ER+ breast cancer cells." (PMID 35757841, 2023).